CISD2 (CDGSH iron sulfur domain 2)
Diseases named in the same sentence as CISD2 in open-access papers (continued):
Sharing a sentence is not in itself a finding about the gene and the disease.
glioma (8 papers, 2018 to 2023). A benign or malignant brain and spinal cord tumor that arises from glial cells (astrocytes, oligodendrocytes, ependymal cells). "The study outcomes indicated that high CISD2 acted as an indicator of adverse prognosis among patients with glioma and was linked to several carcinogenic and immune-related pathways based on functional enrichment analysis." (PMID 35493303, 2022). "As CISD2 expression was linked with OS in patients with glioma, it was of great clinical significance to identify the underlying mechanism." (PMID 35493303, 2022). "Multivariate analysis demonstrated that CISD2 was an independent risk factor for patients with glioma." (PMID 35493303, 2022). "In contrast to normal tissues, CISD2 expression was significantly higher in glioma tissues, and CISD2 presented a certain diagnostic value in distinguishing glioma tissues from normal tissues." (PMID 35493303, 2022). "Multivariate Cox analysis showed that high CISD2 expression was an independent risk factor for poor OS in patients with glioma." (PMID 35493303, 2022). "Our systematic bioinformatics analysis demonstrated that increased expression of CISD2 in glioma was abnormally associated with poor clinicopathological parameters (high histologic grade and malignant histological type)." (PMID 35493303, 2022). "The AUC of ROC analysis was 0.735, indicating that CISD2 has certain diagnostic value in screening glioma tissues from normal tissues." (PMID 35493303, 2022). "Collectively, these results further highlighted that increased CISD2 expression was linked to adverse outcomes in glioma." (PMID 35493303, 2022). "In glioma, reduced tumor cell progression and relapse by knockdown of CDGSH iron sulfur domain 2 (CISD2) was associated with the activation of Beclin 1-mediated autophagy." (PMID 29774126, 2018). "However, the knowledge of how CISD2 affects immune cell infiltration within the TME in glioma remains deficient." (PMID 35493303, 2022). "Furthermore, CISD2 expression was intimately linked to glioma progression and M2 polarization." (PMID 37304867, 2023). "Next, we investigated the effects of CISD2 on immune infiltration levels in patients with glioma using TIMER." (PMID 35493303, 2022). "Human Protein Atlas was used to verify the CISD2 protein level in glioma, and STRING was used to establish relative coexpression gene network." (PMID 35493303, 2022). "CISD2 is overexpressed in many glioma samples and is worthy of further verification in the clinic as a possible diagnostic and prognostic marker." (PMID 35493303, 2022). "In conclusion, our study demonstrates that CISD2 expression levels can be used to diagnose and evaluate the prognosis of patients with glioma." (PMID 35493303, 2022). "In order to develop in-depth knowledge of the clinical significance of CISD2, we analyzed the correlation between it and various clinical features in glioma." (PMID 35493303, 2022). "Prognostic value of CISD2 expression in glioma was identified by the Kaplan-Meier survival curve analysis." (PMID 35493303, 2022). "To increase the comprehension of the biological meaning of CISD2 in glioma, we used the function module of LinkedOmics to examine CISD2 coexpression modes in the glioma cohort." (PMID 35493303, 2022). "In comparison with normal tissues, CISD2 mRNA expression was dramatically increased in glioma tissues." (PMID 35493303, 2022). "To investigate the functions of CISD2 in glioma in-depth, we constructed functional networks based on the coexpressed genes." (PMID 35493303, 2022). "Studies have shown that CISD2 expression is increased in glioma and it can induce the proliferation of glioma cells through inhibiting beclin-1-mediated autophagy." (PMID 35493303, 2022). "We observed that CISD2 was significantly related to most of the markers of Th1, Th2, and Treg cells in LGG, while it was related to rare markers of these cells in GBM, indicating that CISD2 dynamically modulates T lymphocyte immunity with glioma progression." (PMID 35493303, 2022).
glioma (continued). "Our study was to depict the expression profiles of CISD2 and to analyze its latent prognostic role, biological function, and relationship with tumor immune infiltration in patients with glioma." (PMID 35493303, 2022). "The relationships between gene markers of different immune cells and CISD2 expression highlighted the significant meaning of CISD2 in modulating the TME of glioma, especially in LGG." (PMID 35493303, 2022). "CISD2 (CDGSH iron-sulfur domain) promotes glioma cell proliferation via the inhibition of beclin-1-mediated autophagy." (PMID 32992741, 2020). "Hence, we constructed a dynamic PPI network of CISD2-related DEGs to evaluate their cross-action in glioma through STRING." (PMID 35493303, 2022). "This is the first research to investigate the immune role of CISD2 in glioma." (PMID 35493303, 2022). "We found a significantly higher expression of CISD2 in patients achieved with PD than with PR, indicating that CISD2 may take part in pathologic progression of glioma." (PMID 35493303, 2022). "Here, we found that CISD2 is overexpressed in glioma and plays a role in its diagnosis." (PMID 35493303, 2022). "Furthermore, the immunohistochemistry results from HPA revealed that CISD2 showed higher expression in glioma specimens than in normal specimens." (PMID 35493303, 2022). "Furthermore, CISD2 expression was observably correlated to M2 polarization in macrophages with glioma progression." (PMID 35493303, 2022). "CISD2 may be an innovative prognostic biomarker and can act as a potential target for future therapy of glioma." (PMID 35493303, 2022). "CISD2 may be an innovative prognostic biomarker and can act as a potential target for future therapy for glioma." (PMID 35493303, 2022). "The findings reveal that CISD2 may be a promising biomarker and a latent therapeutic target for glioma." (PMID 35493303, 2022). "However, in vivo and in vitro experiments are needed to verify these possible pathways and processes regulated by CISD2 in glioma." (PMID 35493303, 2022). "Our group first comprehensively probed the role of CISD2 in the TME in glioma." (PMID 35493303, 2022). "Collectively, these data indicate that CISD2 may induce M2 polarization in macrophages with glioma progression." (PMID 35493303, 2022). "CISD2 may be involved in the TME through regulating tumor-infiltrating immune cells in glioma." (PMID 35493303, 2022). "This suggests that CISD2 expression may influence the prognosis in patients with glioma." (PMID 35493303, 2022). "Furthermore, the CISD2 level was correlated with age, histologic grade, histological type, isocitrate dehydrogenase (IDH) status, 1p/19q codeletion status, and primary therapy outcome of glioma, while high CISD2 mRNA expression was correlated with grave overall survival." (PMID 35493303, 2022). "However, the knowledge about clinical and prognostic significance of CISD2 in glioma is meager." (PMID 35493303, 2022). "However, the relationship between CISD2 and immune infiltration in glioma remains unclear." (PMID 35493303, 2022). "Thus, it is reasonable to speculate that CISD2 may play a prominent role in glioma." (PMID 35493303, 2022). "Univariate Cox analysis revealed poor OS-related factors, including age > 60 years, high histologic grade, IDH-wild-type, 1p/19q noncodeletion status, and high CISD2 expression in patients with glioma." (PMID 35493303, 2022). "However, our study focuses on the clinical significance without exploring the molecular mechanism of CISD2 in glioma." (PMID 35493303, 2022). "Moreover, the OS was significantly shorter in patients with glioma with higher CISD2 expression than in those with lower CISD2 expression in the IDH-wild-type group and 1p/19q noncodeleted group." (PMID 35493303, 2022).
glioma (continued). "Consistently, we found that the correlation value of a positive relationship between CISD2 expression and CD8+ T cells was significantly decreased with glioma progression in TIMER, indicating that CISD2 might exert an inhibitory effect on CD8+ T cells with tumor progression." (PMID 35493303, 2022). "Consistently, the ssGSEA results showed that CISD2 had a notable and negative relationship with the abundance of CD8+ T cells in glioma." (PMID 35493303, 2022).
hepatocellular carcinoma (8 papers, 2021 to 2024). A malignant tumor that arises from hepatocytes. "In hepatocellular carcinoma, the expression of CISD2 is associated with advanced clinicopathological characteristics, such as tumor size, number of tumors, surgical margin, recurrence, and poor prognosis." (PMID 35493303, 2022). "However, the role of CISD2 in cancer appears context-dependent, whereby it can in certain scenarios in animal studies function as a tumor suppressor and inhibit hepatocellular carcinoma development." (PMID 38263133, 2024). "CISD2 promotes resistance to sorafenib-induced ferroptosis by regulating Beclin1 in hepatoma cells." (PMID 37181755, 2023). "Indeed, CISD2 haploinsufficiency disrupts calcium homeostasis, induces ER stress, and promotes hepatocellular carcinoma (HCC)." (PMID 36430496, 2022). "Our proteomics findings highlight Cisd2 as a novel molecular target for the development of therapies targeting fatty liver diseases, and these new therapies are likely to help prevent subsequent malignant progression to cirrhosis and hepatocellular carcinoma." (PMID 34572415, 2021). "Silencing CISD2 reduced the cell proliferation of resistant hepatocellular carcinoma (HCC) cells by increasing ferroptosis, while inhibiting both CISD2 and BECN1 decreased ferroptosis in HCC cells." (PMID 39605902, 2024).
diabetes insipidus (6 papers, 2014 to 2025). A disorder characterized by excretion of large amounts of urine, accompanied by excessive thirst. "However, Rondinelli and colleagues have now described a patient carrying a homozygous c.103 + 1 CISD2 mutation who developed clinical and biochemical signs of diabetes insipidus." (PMID 28335035, 2017).
gastric cancer (6 papers, 2016 to 2022). A primary or metastatic malignant neoplasm involving the stomach. "In gastric cancer, CISD2 is significantly upregulated and is markedly associated with clinical stage, venous invasion, TNM classification, and lymphatic invasion." (PMID 35493303, 2022). "A recent study also showed that CISD2 is significantly upregulated in gastric cancer, and its expression has been significantly associated with the clinical stage, TNM classifications, venous invasion, and lymphatic invasion." (PMID 33598426, 2020). "The results demonstrate a potential mechanism that underlies the tumor‐suppressor role of CISD2, and it is expected that screening for CISD2 expression combined with chemotherapy drugs will become a new therapeutic strategy for gastric cancer." (PMID 28857517, 2017). "Through an analysis of CISD2 DNA copy number alterations in the Oncomine microarray database, which contains data from gastric cancer patients, a frequent copy number loss of CISD2 was observed in human GC compared with normal gastric tissues." (PMID 28857517, 2017). "Immunohistochemical analysis of 261 paraffin-embedded archived gastric cancer tissues showed that high CISD2 expression was significantly associated with clinical stage, TNM classifications, venous invasion and lymphatic invasion." (PMID 26565812, 2016). "High expression of CISD2 was associated with a significantly increased risk of death in gastric cancer patients (P < 0.001) compared to those with low CISD2 expression by univariate Cox regression analyses." (PMID 26565812, 2016). "Taken together, these findings suggest that the observed regulation of cell cycle and tumorigenesis caused by overexpressing or silencing CISD2 is associated with the AKT/FOXO pathway in gastric cancer cells." (PMID 26565812, 2016). "Moreover, we demonstrated that the pro-proliferative effect of CISD2 on gastric cancer cells was associated with downregulation of cyclin-dependent kinase inhibitor p21Cip1 and p27Kip1, and activation of AKT signaling." (PMID 26565812, 2016). "We analyzed the association between CISD2 and the clinicopathological features of gastric cancer." (PMID 26565812, 2016). "In conclusion, CISD2 is down‐regulated in gastric cancer, and its effects on the inhibition of cellular proliferation, metastatic ability, and increased chemotherapy sensitivity are mediated by antagonism to 5‐FU‐induced autophagy through the AKT/mTOR pathway." (PMID 28857517, 2017). "The presence of CISD2 protein was elevated in patients aged >=60 (P = 0.002), in those with the intestinal type of gastric cancer (P = 0.01), and in those with well‐differentiated cancers (P = 0.049)." (PMID 28857517, 2017). "In this manuscript, we focus on the roles of CISD2 in tumor development, metastasis, and especially its role in the reaction to chemotherapeutic drugs in gastric cancer." (PMID 28857517, 2017). "Here, we have investigated the expression of CISD2 in tumor samples from a large cohort of gastric cancer patients and GC cell lines." (PMID 28857517, 2017). "MTT and colony formation assays both revealed that knockdown of CISD2 significantly reduced the proliferation of gastric cancer cells." (PMID 26565812, 2016). "Specifically in gastric cancer, we found here that CISD2 was upregulated in gastric tumor samples and correlated with the clinical characteristics and prognosis of the disease." (PMID 26565812, 2016). "In our present study, we demonstrated that CISD2 was upregulated in gastric cancer cells and tissues." (PMID 26565812, 2016). "Through analysis of CISD2 expression in published profiles from gastric cancer patients, we found that it was upregulated in gastric cancer samples (409 cases) compared with adjacent normal tissue samples (37 cases) (P < 0.001)." (PMID 26565812, 2016). "Real-time PCR analysis verified that CISD2 mRNA expression was indeed upregulated (by at least 4.8-fold) in cultured gastric cancer cells compared with normal gastric epithelial cells (NGEC)." (PMID 26565812, 2016).
gastric cancer (continued). "Immunostaining analysis showed that the expression level of CISD2 protein in histological sections was significantly correlated with clinical characteristics and reduced survival time of gastric cancer patients." (PMID 26565812, 2016). "Overexpressing CISD2 promoted, while silencing CISD2 inhibited, the proliferation and tumorigenesis of gastric cancer cells by activating the AKT signaling pathway." (PMID 26565812, 2016). "In the current study, we reported that CISD2 mRNA and protein expression levels were significantly upregulated in gastric cancer cells compared to normal gastric epithelial cells (P < 0.001)." (PMID 26565812, 2016). "Overexpressing CISD2 promoted, while silencing CISD2 inhibited, the proliferation of gastric cancer cells." (PMID 26565812, 2016). "In the present study, we reported that the upregulation of CISD2 mRNA and protein expression in gastric cancer cells and human gastric cancer tissues." (PMID 26565812, 2016). "Taken as a whole, our study suggests that CISD2 is a novel marker for the prognosis of early-stage gastric cancer." (PMID 26565812, 2016). "Collectively, these results indicate that overexpression of CISD2 in primary gastric cancer patients correlate with poor survival." (PMID 26565812, 2016). "A similar mechanism may also act in gastric cancer cells, in which CISD2 positively regulates AKT activity." (PMID 28928421, 2017). "Our results suggest that CISD2 plays an important role in human gastric cancer cells and may be a promising chemotherapeutic target for cancer treatment." (PMID 28857517, 2017). "Thus, further studies on the precise roles of CISD2 in human gastric cancer and the clarification of its exact mechanism will help to determine the potential medical applications." (PMID 28857517, 2017). "Furthermore, we found that CISD2 affected cell proliferation and tumorigenicity of gastric cancer cells through mediating the G1-to-S phase transition." (PMID 26565812, 2016). "The findings of this study indicate that CISD2 may promote proliferation and tumorigenicity, potentially representing a novel prognostic marker for overall survival in gastric cancer." (PMID 26565812, 2016). "Taken together, these results strongly indicate that CISD2 is upregulated in human gastric cancer." (PMID 26565812, 2016). "Moreover, we found that ectopic expression of CISD2 promoted gastric cancer cell proliferation and tumorigenesis, while knockdown of endogenous CISD2 inhibited proliferation and tumorigenesis of gastric cancer cells." (PMID 26565812, 2016). "Taken together, these in vitro and in vivo results demonstrate that CISD2 may play an important role in the tumorigenicity of gastric cancer cells." (PMID 26565812, 2016). "Furthermore, ectopic overexpression of CISD2 promoted, while silencing expression of CISD2 inhibited, the proliferation and tumorigenesis in gastric cancer." (PMID 26565812, 2016). "We also analyzed the relative risks indicated by CISD2 in the prognosis of gastric cancer." (PMID 26565812, 2016). "Multivariate analysis revealed that CISD2 expression might be an independent prognostic indicator of survival in gastric cancer patients." (PMID 26565812, 2016). "Furthermore, CISD2 protein expression was dramatically upregulated in all five gastric cancer cell lines tested compared to NGEC by Western blotting." (PMID 26565812, 2016). "It was found that CISD2 was frequently down‐regulated in GC patient samples compared with adjacent normal tissues, which combined with data from a public database showed frequent copy number loss of CISD2 in human gastric cancer." (PMID 28857517, 2017). "Flow cytometry analysis showed that the overexpression of CISD2 significantly decreased, while silencing CISD2 increased, the percentage of cells in the G0/G1 peak but increased that in the S peak, indicating that CISD2 may promote G1-to-S phase transition of gastric cancer cells." (PMID 26565812, 2016).
gastric cancer (continued). "However, the role of CISD2 in gastric cancer is still unknown." (PMID 26565812, 2016). "To verify results of this analysis, we ectopically overexpressed CISD2 in MGC-803 and SGC-7901 gastric cancer cells." (PMID 26565812, 2016). "Among tissues from gastric cancer patients, negative or weak expression of CISD2 protein was found in 123 cases, while 74 cases showed high or moderate expression." (PMID 28857517, 2017). "In an attempt to determine which pathway may be involved in CISD2-mediated gastric cancer progression, GSEA in the published TCGA gastric cancer database (n = 409) was performed." (PMID 26565812, 2016). "Compared to the adjacent non-tumor gastric tissues in which CISD2 was undetectable or found to be only expressed at low levels, CISD2 was overexpressed in the gastric cancer specimens." (PMID 26565812, 2016).